SYT3 (synaptotagmin 3)
Description:
Ca(2+) sensor involved in Ca(2+)-dependent exocytosis of secretory vesicles through Ca(2+) and phospholipid binding to the C2 domain. Ca(2+) induces binding of the C2-domains to phospholipid membranes and to assembled SNARE-complexes; both actions contribute to triggering exocytosis (By similarity). Plays a role in dendrite formation by melanocytes.
Synonyms: SytIII
Tractability: Antibody: UniProt places it where antibodies can reach, with medium confidence; UniProt predicts a signal peptide or a membrane-spanning region; its Gene Ontology location is reachable by antibodies, with medium confidence. PROTAC: its protein half-life has been measured.
Gene: Protein-coding gene on chromosome 19 (50,621,307 to 50,640,040, reverse strand). Ensembl gene ENSG00000213023.
Subcellular location: Cell membrane; Cytoplasmic vesicle, secretory vesicle membrane
Gene Ontology:
Molecular function: protein binding; calcium ion sensor activity; calcium-dependent phospholipid binding; SNARE binding
Biological process: positive regulation of dendrite extension; chemical synaptic transmission; positive regulation of vesicle fusion; regulation of calcium ion-dependent exocytosis; vesicle-mediated transport
Cellular component: endosome; exocytic vesicle; plasma membrane; membrane; synapse; transport vesicle membrane
Genetic constraint (gnomAD): Loss-of-function variants: 20 observed, 38.69 expected, observed/expected ratio (o/e) 0.52, 90% interval 0.36 to 0.75. The upper end of that interval is the gene's LOEUF score, 0.75, which puts it in group 3 of 6, group 1 being the genes least tolerant of losing a copy. Missense variants: 526 observed, 693.17 expected, observed/expected ratio (o/e) 0.76, 90% interval 0.71 to 0.82. Synonymous variants: 297 observed, 309.06 expected, observed/expected ratio (o/e) 0.96, 90% interval 0.87 to 1.06.
Homologues: Orthologues: chimpanzee SYT3 (99% identical), pig SYT3 (98% identical), dog SYT3 (98% identical), macaque SYT3 (98% identical), rat Syt3 (96% identical), guinea pig SYT3 (96% identical), mouse Syt3 (95% identical), zebrafish syt3 (61% identical), tropical clawed frog syt3 (58% identical). Paralogues in human: SYT9 (44% identical), SYT10 (44% identical), SYT6 (42% identical), SYT1 (27% identical), SYT2 (26% identical), SYT5 (25% identical), SYT7 (25% identical), SYT17 (25% identical), SYT11 (23% identical), RPH3A (22% identical), SYT4 (21% identical), SYT15 (20% identical), and 19 more.
Diseases named in the same sentence as SYT3 in open-access papers:
SYT3 is named in the same sentence as 5 diseases in open-access papers, as found by Europe PMC text mining. Sharing a sentence is not in itself a finding about the gene and the disease. The quoted sentences say what the papers report.
depression (1 paper, 2024). "By injecting an viral vector with SYT3 gene, synapses was faster recovered and exhibited an obvious improvement in depression, which demonstrated that SYT3 played a key role in sustaining neurotransmitter release." (PMID 37815908, 2024).
Spasticity (1 paper, 2025). A motor disorder characterized by a velocity-dependent increase in tonic stretch reflexes with increased muscle tone, exaggerated (hyperexcitable) tendon reflexes. "Furthermore, EA was found to reduce SYT‐3 expression, thereby inhibiting the pathogenic role of the SYT‐3/GLUA2 pathway in ICH‐induced spasticity." (PMID 40021946, 2025).
SYT3 also shares sentences with these, for which no sentence is quoted: autism (1 paper); Cerebral ischemia (1); diabetic retinopathy (1).